TNF (tumor necrosis factor)
Diseases named in the same sentence as TNF in open-access papers (continued):
Sharing a sentence is not in itself a finding about the gene and the disease.
infection (continued). "Neutralization of either IFNγ or TNFα was associated with reduced nitric oxide (NO) production, led to uncontrolled bacterial growth and was fatal for C3H/HeN mice upon infection with a normally sublethal dose of R. conorii." (PMID 28222146, 2017). "The risk of infections in RA patients receiving anti-TNF therapy is higher during the first few months following initiation of treatment." (PMID 28264025, 2017). "Male and female innate immunity and acquired immunity are quite different: the male body contains more IL-1β and TNF-α than the female body, but for these cytokines, infection and damage are closely linked." (PMID 28915872, 2017). "Several studies have reported that the relative risk of infection decreases over time in patients with RA treated with anti-TNF." (PMID 29246162, 2017). "IL-12 and TNF possess potent anti-viral property and also promote macrophage activation, while IL-10 plays an important cross-regulatory role during infection associated inflammation." (PMID 28067803, 2017). "TNF, IL-1β and IL-6 are cytokines referred to as pyrogenic and pro-inflammatory cytokines which predominate during infection and inflammation, associated with chronic inflammatory diseases." (PMID 28642550, 2017). "The magnitude of the risk of infection associated with prednisolone dose > 10 mg/day was similar to that associated with TNF-α antagonists." (PMID 28122642, 2017). "In comparison to TNF−/− mice, MT-TNF−/− mice were similarly highly susceptible and rapidly succumbed to infection with >20% body weight loss." (PMID 28280495, 2017). "Inhibition of the antimicrobial actions of IFN-γ, TNF-α and IL-6 are likely to increase the susceptibility of the host to infection." (PMID 28216665, 2017). "Increased levels of CRP, HS-CRP and PCT were associated with infections, as were decreased values of TNF-α and GM-CSF." (PMID 28264059, 2017). "For example, polyfunctional IFN-γ plus TNF-α producing CD8+ T cells with broad ZIKV specificity primed by primary infection can overturn the susceptibility of naive recipient mice after adoptive transfer in vivo." (PMID 29145516, 2017). "Infection of bone marrow-derived macrophages from CLEC5A-deficient mice showed reduced levels of tumor necrosis factor alpha (TNF-α) and IP-10 but elevated alpha interferon (IFN-α) compared to those of wild-type mice." (PMID 27795434, 2017). "TLR3-deficient DCs produced strikingly less TNF-α and IL-10 and exhibited a slight increase in IL-23 secretion 12 hours after infection." (PMID 28973047, 2017). "At initiation of anti-TNF therapy, prescribers need to consider the infection risk in each individual patient, which must take into account the patient’s age, comorbidities, concomitant medications, and clinical history." (PMID 29246162, 2017). "Infection and inflammation play a role in potentiating PH and pro-inflammatory cytokines, including TNF, are associated with severity of PH." (PMID 29263339, 2017). "The data show that rSFV particles encoding murine IFN-γ or TNF-α efficiently inhibited LLC cell growth at 47 h post-infection." (PMID 29276511, 2017). "Recent human data suggests that an absence of an effective Th1 response, characterized by IFN-γ and TNF-α production, leads to monocyte deactivation, excessive CNS chemokine production, and poor clearance of infection with increased risk of IRIS and death." (PMID 28334020, 2017). "Participants in the anti-TNF groups were more accepting of potential side effects (including infections and risk from cancer)." (PMID 28526972, 2017). "We pooled all the 14 studies together that resulted into 3327 confirmed leprosycases and 3203 healthy controls for the assessment of overall associationbetween the TNF -308 G>A polymorphism and risk ofleprosy infection." (PMID 28935761, 2017). "In the diaphragm, infection is associated with increases in inflammatory cytokine expression [tumor necrosis factor-α (TNF-α), interleukin-1β (IL-1β), IL-6, and IL-18] and decreases in contractile performance." (PMID 28659735, 2017).
infection (continued). "The frequencies of the G allele in the −308 position of the promoter region of the TNFα gene was similar between the study groups, while the A allele was found more frequently in individuals with asymptomatic infection (16% vs. 7%)." (PMID 28241747, 2017). "In vitro, IFNγ fuels astrocyte infection by T. cruzi, and IFNγ-stimulated infected astrocytes are implicated as potential sources of tumor necrosis factor (TNF)." (PMID 28877735, 2017). "Pro-inflammatory cytokines, including IFN-γ, TNF-α, IL-6, and IL-1β, are actively produced during the immune response to fight against pathogenic infection." (PMID 28454116, 2017). "The proinflammatory cytokines IL-1β and TNF-α are considered primary mediators of septic shock and are also associated with infection-induced preterm delivery." (PMID 28957335, 2017). "TNF-α peaked early in the lungs of IPS-1−/− mice in response to infection and was associated with the infiltration of neutrophils in the airway lumen prior to the onset of AEC sloughing." (PMID 28539639, 2017). "Second, the same rationale applied to the detrimental effect of TNF inhibition, as increased risk of certain infections among patients on anti-TNF therapies suggested that TNF activity is an essential component of protective immune responses." (PMID 28824652, 2017). "The A allele in TNFα-308G/A SNP was found more frequently in individuals with asymptomatic infection (16% vs 7%), whereas the CC genotype in IL-10-819 C/T SNP was more frequent in patients with CCL (34% vs. 27% in asymptomatic individuals)." (PMID 28241747, 2017). "MASP-2 antibody treatment was associated with lower plasma levels of TNF-α compared to saline at 48 h after infection (median 0.10 vs. 0.25 ng/ml, P = 0.044)." (PMID 28086930, 2017). "Given that TPL-2 is downstream of TLR4 and IL-1R-signaling and that TPL-2-deficent mice are more susceptible to bacterial infection due to reduced TNFα and IL-1β secretions, we analyzed the changes in microbiota following infection of WT and Map3k8–/–mice." (PMID 28759611, 2017). "TNFα deregulation can promote susceptibility to pathogens by impairing pathogen clearance and, ultimately, promoting maintenance of infection and death." (PMID 27351838, 2016). "The risk of infection associated with infliximab and other anti-TNF-alpha agents is well documented." (PMID 27366159, 2016). "In the case of synergistic infection, TNFα is upregulated and causes nuclear translocation of PAD enzymes, resulting in histone deimination and downstream changes in gene regulation." (PMID 26941709, 2016). "The genes encoding FAS and TNFR2 were also highly expressed during infection, together with genes whose products are involved in TNF and NFκB signaling." (PMID 27982111, 2016). "Pulmonary levels of IFNγ, IL-1α, IL-1β and CXCL1/KC were highly increased in TNFα-deficient mice one month after infection, when severe pathology develops, with a reduction of IL-12/23p40 and p19, in line with transcriptome data." (PMID 27853279, 2016). "Elevated levels of TNF-α have been associated with greater morbidity during infection with highly pathogenic virus, and blocking activity of TNF-α attenuates immune-mediated pathology." (PMID 26965109, 2016). "In a mouse model, a fatal course of infection has been associated with an Ehrlichia strain that induces a toxic shock–like syndrome with high serum levels of tumor necrosis factor α." (PMID 27088220, 2016). "Because TNF signals through both TNF-R1 (55 kDa) and TNF-R2 (75 kDa), it has been suggested that TNF-R2 signaling in trypanosomiasis mediates infection-associated pathology, whereas TNF-R1 signaling has little or no impact on the infection outcome." (PMID 27242788, 2016). "As TNF and iNOS were found implicated in determining the dermal infection bottleneck for T. congolense, susceptibility of metacyclic T. brucei parasites to locally produced levels of these effectors would be of interest for further exploration." (PMID 27441553, 2016).
infection (continued). "More relevantly, Humira totally abolished TNF-α mediated antiviral effect against HCV and HEV, providing a possible explanation for the high risk of infection in patients treated with TNF-α inhibitors." (PMID 27150018, 2016). "On the other hand, higher frequencies of Tcm cells producing IFN-γ/TNF-α/IL-2 early after infection were associated with vaccine-elicited protection and bacterial arrest by the host." (PMID 27799930, 2016). "Immunosuppression is likely to have played a role given that patients on anti-TNFα therapy are at increased risk of infection." (PMID 27822400, 2016). "Mucosal invasion of C.albicans in the fetal gut by 3 days after infection was associated with infiltration of immune cells and was paralleled by elevated intestinal levels of TNF-α and IL-17." (PMID 27411776, 2016). "The action of soluble TNFR1 much resembles the anti-TNF-α drugs, suggesting that blocking TNF-α indeed increases bacterial survival in infections and benefits the host by decreasing the damage caused by inflammation." (PMID 27446000, 2016). "Similar to the cell line model, infection of differentiated PBECs caused a significant increase in basolateral release of TNF-α, which correlated with the breakdown of the physical barrier properties." (PMID 27527221, 2016). "The EIEC infection caused a strong p65 phosphorylation at 0.5 h of infection, which was higher (125%) than those responses induced by the positive TNF-α control." (PMID 27774437, 2016). "Taken together, these data showed that infection with N. brasiliensis also ameliorated TNFα-mediated joint inflammation and the resulting bone loss." (PMID 27273006, 2016). "In CL, the immune response is characterized by strong production of IFN-γ and TNF, cytokines that are important for controlling infection but that are also associated with pathogenesis (rev." (PMID 27870860, 2016). "The lungs of TNF deficient miceshowed many large confluent nodules at day 28 post infection, which were morediscrete in M-TNFR1 KO or in mice fully deficient for TNFR1 and less prominentin wild-type controls." (PMID 26931771, 2016). "In fact, NLRC4-/- BMDM were highly susceptible to infection despite secreting more TNF than WT BMDM in response to L. pneumophila infection, possibly due to increased bacterial burden or a failure to undergo pyroptosis." (PMID 27105352, 2016). "We examined the roles of IFNγ, TNFα and LTα in brain microvessel cross-presentation during PbA infection by comparing mice deficient in each cytokine with wild type (WT) C57BL/6J mice." (PMID 26046849, 2015). "This IFN-γ surge is followed by a sudden decrease, most likely associated with a control of the infection, as indicated by a corresponding drop of IL-10 and TNF-α concentration in the serum." (PMID 26566996, 2015). "The expression levels of IL-36α, β, γ, IL-1β, TNF-α and IFN-γ mRNA were next determined in the lungs of WT and TNF-α deficient mice at different time-points following aerogenic infection with M. tuberculosis." (PMID 25950182, 2015). "In conclusion, infection with this A/E pathogen induces mitochondrial dysfunction, which is largely caused by IFNγ and TNFα synergistically compromising complex I and IV levels and activity, via NO generation." (PMID 26481427, 2015). "Increased mortality was associated with impaired TNF-α responses, reduced neutrophil recruitment to the site of infection and increased hyphal growth (Fig3D–G)." (PMID 25637383, 2015). "Here, Cl-CATH2 prominently blocked the genes of LPS–induced key pro-inflammatory cytokines (TNF-α, IL-6, and IL-1β) and iNOS, which can produce NO in a variety of tissues, and detectable in many cell types associated with infection and inflammation." (PMID 26194630, 2015). "We therefore postulated that early host susceptibility of TNF−/− mice was the result of defective activation of innate antigen-presenting immune cells during early infection." (PMID 26112704, 2015).
infection (continued). "In contrast, TNF mRNA levels were higher in Cre- mice compared to IRF-5 deficient mice during the first 2 weeks of infection." (PMID 26046638, 2015). "Increased mortality due to ΔbgsA infection was associated with elevated plasma levels of the inflammatory cytokines TNF-α, IL-6 and MIP-2." (PMID 26172831, 2015). "One of its single nucleotide polymorphisms (SNPs), TNF G-308A, has been associated with severe responses to infection." (PMID 26284064, 2015). "TNF-α is a cytokine involved in the control of infection and is an important factor associated with the immunopathogenesis of disease." (PMID 25706930, 2015). "Other studies have also associated Th1 cytokine expression, including TNF, with asymptomatic infection." (PMID 25875101, 2015). "TNF, IL-1β and IL-6 pro-inflammatory cytokines play crucial roles in inflammation, infection, and responses to stress caused by different types of infections." (PMID 26657940, 2015). "TP4 treatment caused a decrease in TNF and IL-6 at the site of infection on days 1, 2 and 3, as compared with the MRSA infection group." (PMID 25955756, 2015). "Increased susceptibility to infections is a major safety concern with tumor necrosis factor alpha (TNF-α) antagonist treatment." (PMID 26215452, 2015). "Our results suggest that NO generation caused by infection-induced TNFα and IFNγ was the main cause of mitochondrial dysfunction." (PMID 26481427, 2015). "Infection per se, and also in combination with TNFα and IFNγ, caused a reduction in mitochondrial phosphorylation capacity." (PMID 26481427, 2015). "In contrast to TNFf/f mice which survived infection for 15 weeks, TNF−/− mice were highly susceptible and rapidly succumbed to infection within 3 weeks." (PMID 26112704, 2015). "Unexpectedly, S. pyogenes infection of Unc93b1-deficient BMDMs resulted in comparable TNF production as infection of WT cells." (PMID 25756897, 2015). "In contrast, 100% of TNF-α mice died or had to be sacrificed within one month post infection and IL-1R1 deficient mice exhibited an intermediate susceptibility with a 50% survival during the 4 months follow-up period (P = 0.0455)." (PMID 25950182, 2015). "Transcript levels of other Lyme arthritis-associated genes (IFNγ, Cxcl10, TNFα) were very similar between the two strains, and showed a peak in expression at 2 weeks post-infection, followed by resolution at 4 weeks." (PMID 24967703, 2014). "So, further studies at genotype and haplotype levels are needed for a logical explanation regarding association of TNF-α polymorphism with risk of infection." (PMID 24837009, 2014). "When anti-TNFα therapy was combined, especially with CS, the infection risk significantly increased." (PMID 24655394, 2014). "Mounting evidence indicates that the infection-induced production of pro-inflammatory/Th1-cell-polarizing cytokines, including interleukin-1β (IL-1β) and tumor-necrosis factor (TNF), is associated with premature labor and pre-term delivery." (PMID 25139335, 2014). "Infection risk due to decreased cellular immunity in anti-TNFα treated patients, has been shown for other intracellular infections, most notably Mycobacterium tuberculosis, but also Listeria monocytogenes and Salmonella enterica, and for herpesviridae." (PMID 24931640, 2014). "This review concluded that most articles referring to serious infection demonstrated a significantly increased risk of infection in those treated with anti-TNF therapy when compared to conventional DMARD treatment (adjusted hazard ratio 1.0–1.7)." (PMID 25414636, 2014). "In the analysis of the RABBIT German Registry, the risk of serious infections was directly related to the dose of CS, especially when associated with TNFα." (PMID 24655394, 2014). "After seven days of infection, TNF-α was used to treat the infected cells to cause viral reactivation from potential latency, as described in Materials and Methods." (PMID 25243372, 2014).
infection (continued). "The present study reports for the first time the relationship between urinary cytokines IL-6, IFN-γ, TNF-α and IL-10, and S. haematobium infection and infection-associated urinary tract pathology in primary school children." (PMID 25223302, 2014). "Low levels of TNF-α are associated with persistence of infection and greater difficulty in resolution of skin lesion." (PMID 25295285, 2014). "Infection in synergy with HI causes up-regulation of TNFα, nuclear translocation of PAD4 and change in gene regulation as a result of histone deimination." (PMID 24762056, 2014). "Post infection, the susceptible host undergoes a Th1 response whereby over expression of TNF, lymphotoxin (LT) and IFN exacerbates the progression to CM." (PMID 26430675, 2014). "As a consequence, splenocytes from wildtype mice released significantly more TNF-α compared to those from properdin-deficient mice after infection with S. pneumoniae." (PMID 24728387, 2014). "This dropped to a 2.5-fold increase with anti-TNF, corticosteroid and DMARD suggesting that corticosteroids increase the risk of infection when used with anti-TNF." (PMID 25414636, 2014). "In summary, if CR and SJZT are in the diet, there will be a significantly decreased Salmonella load in the organs and blood while also decreasing both TNF-α and IFN-γ levels in serum, as well as the TNF-α levels in the intestinal tissue caused by infection." (PMID 25133542, 2014). "The CS/anti-TNFα combination, therefore, synergizes in lowering TNFα levels through different and independent mechanisms, with consequent enhanced anti-inflammatory effect, but at the expense of a raised infection risk." (PMID 24655394, 2014). "Type-1 cytokine responses (INFγ, TNFα), leading to macrophage activation to produce trypanotoxic NO, are observed during the early stage of infection in both susceptible and resistant mice." (PMID 25375156, 2014). "Pro-inflammatory cytokine TNF is critically involved in the host defense against mycobacterial infection because TNF-deficient mice showed a decreased survival rate and disrupted granuloma formation following an infection by M. tuberculosis." (PMID 24533147, 2014). "Given that TNF production by activated macrophages is partially TLR2-dependent, we next tested the ability of TNF-deficient BMMφ to express cathelicidin upon infection with M. avium or TLR2 activation." (PMID 25400920, 2014). "After both 4 and 8 hours of infection, many of the up-regulated genes were those that encode pro-inflammatory cytokines (IL-1α, IL-1β, IL-6 and TNF-α) and chemokines (CCR7 and IL-8), all of which have been implicated in RA and CVD pathogenesis." (PMID 24874661, 2014). "The ability of DRAG mice to clear the infection was associated with development of antibodies (human IgM and IgG) and TNF-mediated CD4 and CD8 T cell responses to the blood stage parasites." (PMID 25266106, 2014). "Predictors of infection-associated spontaneous preterm delivery include tumor necrosis factor-α (TNF-α), IL-6, IL-1, and IL-8." (PMID 23818902, 2013). "In peritoneal macrophages from a Hri +/+ mouse infected in vitro with these pathogens, TNFα-encoding transcript levels increased >500-fold following a 3-hr infection period." (PMID 23874749, 2013). "Although anti-TNF drug treatment is highly successful, studies conducted in the past ten years indicate that the risk of developing a serious infection is higher among patients taking these drugs, potentially because of the resultant immunosuppression." (PMID 24498926, 2013). "Numerous studies have assessed the increased risk of infection among patients receiving anti- TNF drug therapy." (PMID 24498926, 2013). "For example, those on anti-TNF are at significantly higher risk of serious infection, and there is a theoretical increase in the risk of cancer." (PMID 23663548, 2013).